TACO1 (translational activator of cytochrome c oxidase I)
Description:
Acts as a translational activator of mitochondrially-encoded cytochrome c oxidase 1.
Synonyms: CCDC44; MC4DN8
Tractability: PROTAC: ubiquitination databases record sites on it; its protein half-life has been measured.
Gene: Protein-coding gene on chromosome 17 (63,600,882 to 63,608,365, forward strand). Ensembl gene ENSG00000136463.
Subcellular location: Mitochondrion
Subcellular location (Human Protein Atlas): Mitochondria
Pathways (Reactome):
Metabolism: Complex IV assembly
Gene Ontology:
Molecular function: mitochondrial ribosome binding; protein binding; mRNA binding; rRNA binding
Biological process: positive regulation of mitochondrial translation; regulation of mitochondrial translation
Cellular component: mitochondrion
Genetic constraint (gnomAD): Loss-of-function variants: 14 observed, 25.8 expected, observed/expected ratio (o/e) 0.54, 90% interval 0.36 to 0.85. The upper end of that interval is the gene's LOEUF score, 0.85, which puts it in group 3 of 6, group 1 being the genes least tolerant of losing a copy. Missense variants: 352 observed, 389.34 expected, observed/expected ratio (o/e) 0.9, 90% interval 0.83 to 0.99. Synonymous variants: 149 observed, 155.78 expected, observed/expected ratio (o/e) 0.96, 90% interval 0.84 to 1.1.
Gene-disease validity (ClinGen):
ClinGen rates the evidence that TACO1 causes each of these diseases.
mitochondrial disease (autosomal recessive): Definitive.
Leigh syndrome (autosomal recessive): Moderate. A progressive neurological disease defined by specific neuropathological features associating brainstem and basal ganglia lesions.
Homologues: Orthologues: chimpanzee TACO1 (99% identical), macaque TACO1 (94% identical), dog TACO1 (85% identical), mouse Taco1 (77% identical), rat Taco1 (77% identical), guinea pig TACO1 (76% identical), pig TACO1 (66% identical), tropical clawed frog taco1 (47% identical), zebrafish taco1 (42% identical), Caenorhabditis elegans taco-1 (27% identical), Drosophila melanogaster CG4957 (20% identical).
Diseases named in the same sentence as TACO1 in open-access papers:
TACO1 is named in the same sentence as 20 diseases in open-access papers, as found by Europe PMC text mining. Sharing a sentence is not in itself a finding about the gene and the disease. The quoted sentences say what the papers report.
Leigh syndrome (9 papers, 2012 to 2024). "On the other hand, mutations in TACO1 result in premature stop codons manifesting as a late-onset juvenile form of Leigh syndrome, also associated with COX deficiency." (PMID 39036954, 2024). "Here, we show that the missing factor is TACO1, a protein causative of a juvenile form of neurodegenerative Leigh's syndrome associated with cytochrome c oxidase deficiency, until now believed to be a translational activator of COX1 mRNA." (PMID 39036954, 2024). "Given that human and mouse TACO1 null mutations cause late-onset Leigh syndrome, we expected that dpc29Δ yeast cells would have a respiratory growth phenotype." (PMID 36620885, 2023). "In mouse and human cells, the loss of TACO1 causes severe defects in Cox1 protein levels, resulting in late-onset Leigh syndrome." (PMID 36620885, 2023). "To evaluate the effects of infection on mitochondrial disease we used a mouse model of Leigh Syndrome, where a missense mutation in the Taco1 gene results in the loss of the translation activator of cytochrome c oxidase subunit I (TACO1) protein." (PMID 32130224, 2020). "Mutations in the translational activator of cytochrome c oxidase subunit I (TACO1) causes cytochrome c oxidase deficiency and Leigh Syndrome in patients." (PMID 27319982, 2016). "Defects in TACO1 result in cytochrome C oxidase deficiency and late-onset Leigh syndrome." (PMID 38531971, 2024). "TACO1 is required for translation of the COX-I subunit of complex IV, and TACO1 deficiency results in a complex IV defect, which may, in turn cause Leigh syndrome." (PMID 38240888, 2024). "TACO1 is reported to act as a cytochrome c oxidase subunit 1 (Cox1)-specific translational activator whose loss results in decreased Cox1 protein levels in cells and late-onset Leigh syndrome in humans and mice." (PMID 36620885, 2023). "A homozygous mutation in the TACO1 gene has been identified in patients suffering from Leigh Syndrome (LS) who have an isolated cytochrome c oxidase (or complex IV) deficiency that leads to progressive cognitive dysfunction, dystonia and visual impairment." (PMID 32130224, 2020). "At most, a single gene had five independently associated SNPs, i.e., expression of TACO1 (Syn CCDC44), translational activator of mitchondrially encoded cytochrome c oxidase subunit I, a gene with a role in Leigh Syndrome, was independently associated with five SNPs in LWK." (PMID 22532805, 2012).
Ataxia (1 paper, 2020). Ataxia refers to impaired coordination of voluntary muscle movement. "In summary, TACO1 mutations present with a childhood-onset, slowly progressive spastic paraparesis, ataxia and optic neuropathy with characteristic cystic white matter lesions in the periventricular area and cerebellum." (PMID 32444556, 2020).
cardiac hypertrophy (1 paper, 2016). "The Taco1 mutant mice develop a late-onset visual impairment, motor dysfunction and cardiac hypertrophy and thus provide a useful model for future treatment trials for mitochondrial disease." (PMID 27319982, 2016).
cardiomyopathy (1 paper, 2023). A disease of the heart muscle or myocardium proper. "Twelve of the 52 mouse models identified with cardiomyopathy (Acadv1, Fxn, Mto1, Taco1, Hmgcs2, Mpv17, Opa1, Pnpla8, Tmem126b, Gpd2, Mpv17, Micu1) showed that the presence of cardiomyopathy can be dependent on the degree of stress." (PMID 37103033, 2023).
cytochrome c oxidase deficiency (1 paper, 2024). "Our study, therefore, sheds light on the molecular mechanism underlying TACO1-related mitochondrial encephalopathy associated with cytochrome c oxidase deficiency." (PMID 39036954, 2024).
lymph node metastasis (1 paper, 2025). "Additionally, elevated TACO1 protein levels are associated with higher histological grade, T stage, lymph node metastasis, and a higher likelihood of cancer recurrence in BCa." (PMID 39656941, 2025).
melanoma (1 paper, 2012). A malignant, usually aggressive tumor composed of atypical, neoplastic melanocytes. "In addition, we investigated the expression levels of the COXI (complex IV), the downstream effector of TACO-1, whose expression was suppressed in Elesclomol-treated melanoma cells." (PMID 22912665, 2012). "The authors would like to thank Dr. Soldano Ferrone, University of Pittsburgh, and Dr. Antoni Ribas, UCLA, for providing the MV3 and M233 melanoma cell lines, respectively, and Dr. Eric Shoubridge, McGill University, for providing the rabbit anti-human polyclonal antibody against TACO-1." (PMID 22912665, 2012). "To investigate the subcellular origin of HIF-1α and TACO-1, we performed immunoblot analysis comparing whole-cell lysates with mitochondrial extracts prepared from Elesclomol-treated melanoma cells, which showed that TACO-1 was decreased in mitochondrial extracts." (PMID 22912665, 2012). "HO-1 was upregulated in 3/3 melanoma cell lines (WM1158, WM983-B, and WM852); TACO-1 was downregulated in WM1158 melanoma cells and not detectable in two melanoma cell lines (Lu1205 and WM983-B) (data not shown); and HIF-1α was upregulated in 3/3 melanoma cell lines (WM1158, WM983-B, TPF10-741)." (PMID 22912665, 2012).
viral infection (1 paper, 2020). "We infected Taco1 mutant and wild-type mice with a murine cytomegalovirus and show that a common viral infection exacerbates the complex IV deficiency in a tissue-specific manner." (PMID 32130224, 2020). "The Taco1 mutation reduced Complex IV activity and this reduction was not further exacerbated by the infection indicating that chronic viral infection can further promote the Complex IV deficiency." (PMID 32130224, 2020). "We used our Taco1 model of MD, to investigate the effects of a common viral infection on the onset and progression of MD." (PMID 32130224, 2020).
mitochondrial disease (7 papers, 2016 to 2025). "The identification of two Turkish families with similar characteristic clinical presentation and an additional homozygous nonsense mutation confirms that TACO1 is a human mitochondrial disease gene." (PMID 32444556, 2020). "Recently we developed a model of mitochondrial disease that is caused by a mutation in a nuclear gene encoding the translational activator of cytochrome c oxidase subunit 1 (TACO1)." (PMID 32130224, 2020). "While cellular TACO1 decrease could be explained by misprocessing or premature degradation of the corresponding RNA, TACO1 deficiency has previously been linked to cytochrome c/complex IV deficiency and mitochondrial disease." (PMID 38240888, 2024). "When modeled in mice, a Taco1 mutation that resulted in TACO1 loss caused similar late-onset pathologies affecting vision, motor function and learning capacity that could be further exacerbated by infection mimicking sudden triggers of mitochondrial diseases." (PMID 38779771, 2024). "Late detection of assembly factors with severe phenotype includes genes such as NDUFAF3, SURF1, TACO1, SCO1, LYRM7, or TIMMDC1, whose mutations are commonly found in patients with mitochondrial diseases (Fig. EV2F)." (PMID 40301572, 2025). "Although TACO1 has been identified as a mitochondrial disease gene, the function of the TACO1 protein is poorly understood." (PMID 27319982, 2016). "In 2009, we identified TACO1 as a novel mitochondrial disease gene in a single family, however no second family has been described to confirm the role of TACO1 in mitochondrial disease." (PMID 32444556, 2020).
cancer (2 papers, 2021 to 2025). A tumor composed of atypical neoplastic, often pleomorphic cells that invade other tissues. "Prior research linked TACO1 deficiency to mitochondrial dysfunction and human mitochondrial disorders, but its involvement in cancer was unexplored." (PMID 39656941, 2025). "The mutations at the binding sites of TACO1‐circFOXK2‐HSP90β disturb the ternary complex and inhibit cancer stemness and cisplatin resistance in BCa cells by suppressing the MTCO1/OXPHOS/mtROS axis." (PMID 39656941, 2025). "Moreover, a notable downregulation of SOX2, a key driver gene of cancer stemness, was observed following the knockdown of TACO1 in BCa‐CIS cells." (PMID 39656941, 2025). "Consequently, disrupting the TACO1‐circFOXK2‐HSP90β complex inhibits cancer stemness and cisplatin resistance in BCa cells by suppressing the MTCO1/OXPHOS/mtROS axis." (PMID 39656941, 2025). "Nonetheless, whether TACO1 plays a specific role in cancer still remains elusive." (PMID 33923185, 2021). "Therefore, treatments targeting POLRMT and TACO1 need to be evaluated in relation to whether they have a selective inhibitory effect on cancer cells, including BA in this study." (PMID 33923185, 2021). "In BCa cells, our findings demonstrate that TACO1‐mediated OXPHOS increases mtROS, a major source of intracellular ROS, thereby promoting cancer cell stemness and cisplatin resistance via SOX2 upregulation." (PMID 39656941, 2025). "Mechanistically, mitochondrial TACO1 enhances the translation of the mitochondrial cytochrome c oxidase I (MTCO1), promoting mitochondrial reactive oxygen species (mtROS) by upregulating OXPHOS, consequently driving cancer stemness and cisplatin resistance." (PMID 39656941, 2025).
infection (2 papers, 2020 to 2024). The state of being infected such as from the introduction of a foreign agent such as serum, vaccine, antigenic substance or organism. "In the presence of infection, we identified downregulation of the mTOR signalling pathway via its downstream targets, S6 and 4EBP1, in the livers of Taco1 mutant mice." (PMID 32130224, 2020). "The levels of TACO1 were dramatically lowered in the presence or absence of infection and there was a reduction in the abundance of COXI in the hearts and livers (respectively) of Taco1mut/mut mice from both groups compared to their respective control mice." (PMID 32130224, 2020).
tumor (1 paper, 2025). "Consistent with our in vitro findings, data from subcutaneous tumor formation and orthotopic BCa models demonstrated that TACO1 knockdown inhibited the tumor‐initiating capacity and cisplatin resistance of T24‐CIS cells in vivo." (PMID 39656941, 2025).
TACO1 also shares sentences with these, for which no sentence is quoted: Bladder Cancer (1 paper); esophageal squamous cell carcinoma (1); heart failure (1); Hypertension (1); Mitochondrial encephalopathy (1); Onset (1); Optic neuropathy (1); Spastic paraparesis (1).